LEP (leptin)
Diseases named in the same sentence as LEP in open-access papers (continued):
Sharing a sentence is not in itself a finding about the gene and the disease.
liver fibrosis (continued). "Adipokine pathways and inflammatory markers like adiponectin, leptin, and IL-6 are the focus of the green cluster, which is closely related to histological evaluations of cirrhosis and hepatic fibrosis." (PMID 40868109, 2025). "In contrast, the ROC curve showed that serum leptin cannot detect liver fibrosis (p-value = 0.76), with an AUROC of 0.52 at 95% confidence." (PMID 38738048, 2024). "Leptin, another adipokine, influences hepatic stellate cell activation, liver fibrosis, energy balance, and appetite suppression, and elevated leptin levels are observed in individuals with increased body fat and cardiometabolic disorders." (PMID 38397999, 2024). "Nonetheless, leptin has effects on liver fibrosis in animal models and ObRb is localized in Kupffer and stellate cells, indicating a delicate situation between lipid mobilization and possible development of fibrosis." (PMID 36674935, 2023). "This study aimed to investigate the mechanisms of liver fibrosis and NAFLD caused by Leptin deficiency." (PMID 37705071, 2023). "Recent work has demonstrated that disrupting histamine/leptin signaling can prevent cholangiocyte damage and hepatic fibrosis in HFD-fed mice." (PMID 38085726, 2023). "Loss of LEPTIN in pigs led to β-oxidation and oxidative stress and, in combination with AMPK mediated mitochondrial autophagy, increased liver fibrosis." (PMID 37705071, 2023). "Preclinical studies have documented that leptin enhances neovascularization through a VEGF-dependent pathway in parallel with the induction of liver fibrosis and hepatocarcinogenesis." (PMID 37834153, 2023). "Leptin resistance is another common condition in NAFLD and hypopituitarism and leptin levels correlate with the severity of liver fibrosis in surgical-hypopituitarism patients." (PMID 36419770, 2022). "Previous studies using rodents also underscored an important role of leptin in driving the formation of liver fibrosis." (PMID 36499091, 2022). "Leptin has been shown to modulate the fibroblastic and inflammatory processes of hepatic cholestasis, hepatic fibrosis, and chronic allergic airway disease." (PMID 36295022, 2022). "The mechanism of GLP-1RA on hepatic fibrosis can be attributed partly to the decrease in pro-inflammatory adipokines such as leptin, (monocyte chemoattractant protein-1and resistin, which are associated with the progression to NASH and fibrosis." (PMID 33897616, 2021). "Leptin also promotes liver fibrosis by inducing Transforming Growth Factor β (TGF-β) and connective tissue growth factor in HSCs." (PMID 33671547, 2021). "Leptin has a potent mitogen activity on hepatic cells, inhibitis stellate cells apoptosis, and promotes the liver fibrosis processes." (PMID 33584134, 2021). "Once the hepatic stellate cell is activated, it can also produce more leptin and further strengthen the fibrogenesis cascade, eventually leading to more liver fibrosis and cirrhosis." (PMID 33557355, 2021). "Leptin administration has been shown to enhance liver fibrosis by increasing the expression of procollagen-I, TGFβ1 and smooth muscle actin and amplify inflammation by increasing the systemic levels of TNF-α in experimental models." (PMID 32933141, 2020). "For our investigation of the associations of serum adiponectin values and serum leptin values with serum soluble TNFR-2 levels, we examined 10 of the 15 patients' values and determined their correlation with liver fibrosis." (PMID 33102399, 2020). "During liver fibrosis, the role of leptin and its functioning receptors, in particular in activated hematopoietic stem cells (HSCs), has been demonstrated." (PMID 33324348, 2020). "Ob/ob mice are protected from fibrosis because leptin is a mediator of hepatic fibrosis during chronic toxic liver injury." (PMID 33324348, 2020). "In contrast, these patients' serum leptin levels showed a significant correlation with their liver fibrosis grades (R = 0.696, p=0.025) (–3)." (PMID 33102399, 2020).
liver fibrosis (continued). "The adipose tissue is also an endocrine organ that secretes hormone such as leptin, which plays an important role in the regulation of body fat and in the development of hepatic fibrosis." (PMID 31888144, 2019). "When FoxO1 was unphosphorylated, it increased levels of miR-122 and suppressed leptin-dependent HSC activation as well as liver fibrosis in ob/ob mice." (PMID 31408957, 2019). "Irisin, which is an exercise-induced myokine, converts white adipose to brown adipose tissue and leptin, which is secreted by fat mass, affects liver fibrosis through chronic inflammation." (PMID 31835362, 2019). "Accumulative evidence have shown that leptin plays a crucial role in the development of liver fibrosis." (PMID 29515462, 2018). "Activated HSCs were able to secrete leptin, thus establishing a vicious cycle that further promotes liver fibrosis." (PMID 29910742, 2018). "Leptin can not only promote the development of liver fibrosis, but also promote the development of HCC by activating JAK/STAT pathway and ERK pathway." (PMID 31205932, 2018). "For example, leptin can induce liver fibrosis through the activation of hepatic stellate cells (HSCs)." (PMID 30563531, 2018). "Accumulating evidence reveals that hormone leptin, mainly produced by adipocyte, plays a unique role in promotion of liver fibrosis." (PMID 27709831, 2017). "It is noteworthy that activated HSCs secrete VEGF and angiopoietin-1 to promote angiogenesis in the model of murine liver fibrosis or exposure to leptin." (PMID 29156788, 2017). "In the HIAT group, the levels of ferritin, an inflammatory marker, and the levels of leptin, an adipokine that induces inflammatory reactions and hepatic fibrosis, were significantly reduced after the training." (PMID 28223710, 2017). "One of the proposed mechanisms of OPN-induced hepatic fibrosis was via the enhancement of leptin-mediated fibrogenesis." (PMID 28051126, 2017). "There is increasing evidence that leptin augments inflammatory and profibrogenic responses to hepatic injury whilst downregulation of leptin decreases liver fibrosis." (PMID 26798417, 2016). "During hepatic fibrosis, leptin suppresses the expression and activity of the collagen-degrading MMPs, such as MMP2, and promotes the expression of TIMP1, an important negative regulator of MMP2." (PMID 24982243, 2014). "Leptin is a proinflammatory cytokine that accelerates the progression of hepatic fibrosis and exacerbates the inflammatory process in the liver." (PMID 24524410, 2014). "Leptin has been reported to be a potent hepatic stellate cell mitogen and inhibit hepatic stellate cell apoptosis, which promotes the pathogenesis of liver fibrosis." (PMID 24733068, 2014). "In liver injury, leptin has a proinflammatory role and is considered to be an essential mediator of liver fibrosis." (PMID 23805238, 2013). "Leptin is also reported to be a mediator of liver fibrosis after chronic liver injury in mouse models." (PMID 23690838, 2013). "The mechanisms involved in the increase of leptin according to the stage of hepatic fibrosis are obscure." (PMID 17540037, 2007). "CONCLUSIONS: In summary, serum vitamin D and leptin could serve as a valuable supplemental biomarker for predicting the liver fibrosis." (PMID 41721256, 2026). "Leptin showed no consistent association with liver fibrosis markers (kPa measurements) across SLD categories." (PMID 40956476, 2025). "Leptin and its receptor play an important role in driving the formation of liver fibrosis." (PMID 37705071, 2023). "Unlike leptin deficiency in rodents, which does not result in hepatic fibrosis, LEPTIN−/− pigs developed the phenotypic features of fatty liver, NASH, and hepatic fibrosis with age." (PMID 36499091, 2022). "Leptin is increased in obesity and is an important mediator of hepatic fibrosis in response to chronic liver injury, whether metabolic or toxic in etiology." (PMID 36612019, 2022).
liver fibrosis (continued). "Furthermore, leptin-mediated neovascularization coordinates with vascular endothelial growth factor (VEGF) an important role in the development of liver fibrosis and hepatocarcinogénesis in NASH." (PMID 36612019, 2022). "However, the leptin gene mutations alone cannot induce NAFLD, special diets, such as MCD, are further needed, Nevertheless, ob/ob mice with MCD fail to induce the liver fibrosis phenotype." (PMID 35721478, 2022). "Adiponectin and leptin are adipokines with a function in liver fibrosis." (PMID 33461570, 2021). "In animal models, the lack of leptin causes a reduction of liver damage, while an increase of its concentration causes hepatic fibrosis." (PMID 33584134, 2021). "The impact of BMI on leptin and its influence on liver fibrosis remain controversial." (PMID 34249975, 2021). "It has been reported in various studies that the increase in leptin stimulates liver fibrosis." (PMID 34616224, 2021). "The observed anti-inflammatory effect in WAT and lowered circulating leptin levels in the current study could therefore also indirectly have contributed to the attenuation of hepatic inflammation and liver fibrosis with BU." (PMID 34944770, 2021). "Furthermore, leptin promotes the progression of liver fibrosis by stimulating the synthesis of transforming growth factor beta (TGFß) in the Kupffer cells." (PMID 33557355, 2021). "Likewise, leptin modulates the expression of other metalloproteinases that play a crucial role in liver fibrosis." (PMID 33316927, 2020). "The significant correlation that was revealed between the serum leptin levels and liver fibrosis supports this speculation." (PMID 33102399, 2020). "Moreover, leptin was proven to downregulate miR-122 in HSCs also via the Hedgehog pathway, while miR-122 abolished leptin-mediated liver fibrosis in ob/ob mice." (PMID 31408957, 2019). "Moreover, VEGF and angiopoietin-1, produced by activated HSCs, have been shown to trigger angiogenesis in a murine model with liver fibrosis or following exposure to leptin." (PMID 31455001, 2019). "Liver fibrosis was less evident after leptin administration and caloric restriction." (PMID 30818874, 2019). "Leptin promotes the liver fibrosis, but adiponectin prevents the progress of liver fibrosis." (PMID 31205932, 2018). "Moreover, leptin was reported as potent HSCs mitogen and to prevent HSCs apoptosis, hence promoting the pathogenesis of hepatic fibrosis." (PMID 29910742, 2018). "The preventive effect of AMPK on hepatic fibrosis was further evidenced by the fact that an adipocytokine adiponectin could disrupt leptin-mediated hepatic fibrosis through the activation of AMPK in HSC." (PMID 27239214, 2016). "Moreover the level of leptin, which also has pro-inflammatory properties and is considered an essential mediator of hepatic fibrosis, was significantly higher in HFHF than in HFD rats, despite the same weight gain for each group." (PMID 26918024, 2016). "The ob/ob mice, in which leptin is knocked out, developed less severe liver fibrosis induced by either CCl4 or thioacetamide (TAA), but when leptin levels were restored liver fibrosis was aggravated, suggesting that leptin is a potential pro-fibrogenic adipocytokine." (PMID 22934006, 2012). "Furthermore, it has been shown that leptin can promote the phenotypic transition of HSCs by activating the Hh pathway, altering gene expression programs that promote liver fibrosis." (PMID 22934006, 2012). "Additionally, mounting evidence suggests that leptin may play a role in hepatic fibrogenesis, with circulating leptin concentrations showing independent correlations with liver fibrosis severity in overweight and obese individuals." (PMID 40956476, 2025). "Taken together, our findings suggest that CCl4 exposure could not aggravate hepatic fibrosis in leptin-deficient ob/ob mice." (PMID 39832399, 2025).
liver fibrosis (continued). "Firstly, the cross-sectional observational design prevents establishing causal relationships between leptin and liver fibrosis, and does not allow causal inferences to be drawn; it remains possible that hyperleptinemia is a consequence rather than a determinant of liver fibrosis." (PMID 40507178, 2025). "Notably, leptin is a pro-fibrotic protein and induces cardiac and liver fibrosis." (PMID 37884762, 2024). "Interestingly, published studies and data presented in this study demonstrate that, in contrast with pigs, Leptin deficiency in rodents does not result in hepatic fibrosis." (PMID 37705071, 2023). "However, leptin is not an essential factor since leptin deficiency reduces but does not eliminate the development of liver fibrosis in infected mice." (PMID 33316927, 2020). "Therefore, reducing circulating leptin levels by exercise training might contribute to ameliorating liver fibrosis in subjects with NAFLD." (PMID 30374329, 2018). "Additionally, mice receiving the treatment of recombinant leptin promoted fibrogenic response, whereas leptin receptor-deficient rats failed to develop liver fibrosis." (PMID 29436483, 2018). "Our purpose was to illustrate that the effects of plumbagin on alleviating phenotype changes and dysfunction in the leptin-stimulated LSEC were achieved via the decreased expression of ET-1, VEGF, LN, and type IV collagen, effectively alleviating the mechanism causative of hepatic fibrosis." (PMID 28770223, 2017). "In line with this assumption, the application of leptin was associated with significant enhanced TAA-induced liver disease, while the application of a competitive leptin inhibitor attenuated chemically induced hepatic fibrosis in mice and suppressed profibrogenic potential of HSC." (PMID 26779021, 2015). "Thus, our data supports the hypothesis that WD-induced increases in leptin levels may precede and even be permissive for subsequent liver fibrosis to occur with a longer term WD challenge." (PMID 26519296, 2015). "However, several studies show that leptin is essential for the deposition of hepatic fibrosis." (PMID 22829877, 2012). "In a thioacetamide- and leptin-induced liver fibrosis model, DCs activated hepatic stellate cells, NKT cells, and T cells by producing TNF-α, thus promoting the progression of liver fibrosis." (PMID 36032154, 2022). "Indeed, the underlying differences between leptin and leptin receptor deficiency are not yet explored, as details associating leptin signals and metabolic disorder remain poorly understood, especially those related to liver fibrosis or cancers." (PMID 35721478, 2022). "Increased angiogenesis lead by leptin has been demonstrated in rats, where leptin-mediated neovascularization coordinated with VEGF plays an important role in the development of liver fibrosis and hepatocarcinogenesis in NASH." (PMID 33316927, 2020). "On the other hand, leptin also upregulated miR-27a/b-3p levels in hepatic stellate cells and increased both α-SMA and α1(I) collagen expression promoting liver fibrosis." (PMID 33316927, 2020). "Our results are also in agreement with literature data showing a role for JAK/STAT pathway in the modulation of liver fibrosis, as in the case of STAT3 activation in hepatic stellate cells treated with IL-6 and leptin." (PMID 31861914, 2019). "Leptin can promote an inflammatory response by activating the secretion of proinflammatory cytokines, such as TNF-α, IL-6, and IL-12 in liver fibrosis." (PMID 29436483, 2018). "The plasma level of leptin increased along with increased fat mass in AKO mice, which partially explains the aggravating progression of liver fibrosis in AKO mice." (PMID 29515462, 2018). "In this study, we also found that leptin enhances ET-1, VEGF, LN, and type IV collagen expression, and all of these have been used to induce liver fibrosis." (PMID 28770223, 2017).
liver fibrosis (continued). "For example, plasma leptin, TNF-α and IL-6 levels positively correlate with hepatic injury and fibrosis deposition in WAT and the liver, while adiponectin attenuates hepatic fibrosis." (PMID 26891322, 2016). "One approach utilizes the testing of biochemical markers of liver fibrosis: hyaluronic acid, adiponectin, high-sensitivity CRP, type IV collagen, serum IL-6, leptin, laminin, c-peptide, and cytokeratin-18." (PMID 23555578, 2013). "Hence the increased levels of GIP, adipsin and insulin as well as of leptin, that augments insulin signal transduction, are mainly correlated not only between them but also with the decreased levels of ghrelin that has been indicated as marker of the liver fibrosis progression." (PMID 22745767, 2012). "The association between leptin levels and nonalcoholic fatty liver disease (NAFLD)-related liver fibrosis is not well proven." (PMID 39272729, 2024). "In our study, patients with liver fibrosis did not have higher leptin levels (14.2 vs. 11.2; p = 0.2)." (PMID 38792501, 2024). "In our pilot study, non-significantly elevated levels of leptin in significant hepatic fibrosis (>=F2) were detected." (PMID 39272729, 2024). "Patients presenting MAFLD with liver fibrosis display major alterations in adipokine profile such as lower adiponectin levels or increased leptin levels, in comparison to patients without morbid obesity." (PMID 36120456, 2022). "Repeated exposure to high leptin and low adiponectin due to increased adiposity could be involved in NAFLD progression, hepatic fibrosis and the altered immune response and angiogenesis, which eventually result in hepatic carcinogenesis." (PMID 34108574, 2021). "miR122 was demonstrated to inhibit liver fibrosis and reduced HSC proliferation; however, leptin treatment was able to reduce its expression in HSC both in vitro and in vivo through the hedgehog signaling pathway and by inducing the phosphorylation of FoxO1 via PI3K/Akt signaling pathway." (PMID 33316927, 2020). "Fibrosis develops in the absence of leptin in ob/ob mice; therefore, liver fibrosis depends on the presence of leptin in chronic liver damage." (PMID 33324348, 2020). "Leptin (200 nM) increased the expression of TGF-β1 in KCs and sinusoidal endothelial cells, and connective tissue growth factor in KCs, being KCs-HSCs cross-talk proposed for liver fibrosis." (PMID 29910742, 2018). "In ob/ob mice, the congenital absence of leptin abrogated the development of CCl4-induced hepatic fibrosis comparing to lean littermates, which is reverted by leptin treatment (100 ng/ml)." (PMID 29910742, 2018). "Enhanced leptin expression may be one of mechanisms by which SGE ameliorated NAFLD and hepatic fibrosis in HFD rats." (PMID 23476686, 2013). "Interestingly, leptin was reported to activate p38 MAPK, which leads to the enhanced expression of collagen and is possibly followed by liver fibrosis." (PMID 22952896, 2012). "A limitation of the leptin-deficient ob/ob and DIO models is that the mice do not develop steatohepatitis or liver fibrosis as is observed in humans." (PMID 23056165, 2012). "However, clinical evidence linking circulating leptin levels to liver fibrosis in overweight or obese individuals without overt comorbidities remains scarce and often inconsistent." (PMID 40507178, 2025). "Therefore, β-oxidation, mitochondrial autophagy and hepatic fibrosis did not occurred in Leptin−/− rat livers." (PMID 37705071, 2023). "Indeed, liver fibrosis was only recovered by exogenous administration of leptin, but not by the correction of the obese phenotype by dietary manipulation." (PMID 33316927, 2020). "Therefore, leptin may be a potentiating, but not an essential factor in the development of hepatic fibrosis." (PMID 39832399, 2025). "Doing so, we found that the deletion of adiponectin in HSCs accelerates the development of liver fibrosis as reflected by significant increases in SMA, Col1a1, Col3a1, Col4a4, and leptin, but not TGF-β expression in the liver." (PMID 39792554, 2025).